AP4B1 (adaptor related protein complex 4 subunit beta 1)
Description:
Component of the adaptor protein complex 4 (AP-4). Adaptor protein complexes are vesicle coat components involved both in vesicle formation and cargo selection. They control the vesicular transport of proteins in different trafficking pathways. AP-4 forms a non clathrin-associated coat on vesicles departing the trans-Golgi network (TGN) and may be involved in the targeting of proteins from the trans-Golgi network (TGN) to the endosomal-lysosomal system. It is also involved in protein sorting to the basolateral membrane in epithelial cells and the proper asymmetric localization of somatodendritic proteins in neurons. AP-4 is involved in the recognition and binding of tyrosine-based sorting signals found in the cytoplasmic part of cargos, but may also recognize other types of sorting signal (Probable).
Synonyms: BETA-4; CPSQ5; SPG47
Tractability: Antibody: UniProt places it where antibodies can reach, with high confidence. PROTAC: ubiquitination databases record sites on it; its protein half-life has been measured.
Gene: Protein-coding gene on chromosome 1 (113,894,194 to 113,905,722, reverse strand). Ensembl gene ENSG00000134262.
Subcellular location: Golgi apparatus, trans-Golgi network membrane
Subcellular location (Human Protein Atlas): Vesicles
Pathways (Reactome):
Vesicle-mediated transport: Golgi Associated Vesicle Biogenesis; Lysosome Vesicle Biogenesis
Gene Ontology:
Molecular function: protein binding; clathrin binding
Biological process: endocytosis; intracellular protein localization; protein targeting; vesicle-mediated transport; intracellular protein transport; protein localization to somatodendritic compartment; protein transport
Cellular component: AP-4 adaptor complex; cytoplasmic side of trans-Golgi network transport vesicle membrane; cytosol; trans-Golgi network; endosome lumen; trans-Golgi network membrane; clathrin adaptor complex; Golgi apparatus; membrane coat
Genetic constraint (gnomAD): Loss-of-function variants: 49 observed, 80.04 expected, observed/expected ratio (o/e) 0.61, 90% interval 0.49 to 0.78. The upper end of that interval is the gene's LOEUF score, 0.78, which puts it in group 3 of 6, group 1 being the genes least tolerant of losing a copy. Missense variants: 911 observed, 952.57 expected, observed/expected ratio (o/e) 0.96, 90% interval 0.9 to 1.01. Synonymous variants: 330 observed, 351.15 expected, observed/expected ratio (o/e) 0.94, 90% interval 0.86 to 1.03.
Gene-disease validity (ClinGen):
ClinGen rates the evidence that AP4B1 causes each of these diseases.
AP-4 deficiency syndrome (autosomal recessive): Definitive.
Homologues: Orthologues: chimpanzee AP4B1 (99% identical), macaque AP4B1 (99% identical), dog AP4B1 (95% identical), pig AP4B1 (94% identical), rabbit AP4B1 (93% identical), mouse Ap4b1 (91% identical), rat Ap4b1 (91% identical), guinea pig AP4B1 (89% identical), tropical clawed frog ap4b1 (66% identical), zebrafish ap4b1 (57% identical), Caenorhabditis elegans apb-3 (22% identical), Drosophila melanogaster rb (22% identical). Paralogues in human: AP2B1 (29% identical), AP1B1 (28% identical), AP3B2 (23% identical), AP3B1 (23% identical).
Diseases named in the same sentence as AP4B1 in open-access papers:
AP4B1 is named in the same sentence as 27 diseases in open-access papers, as found by Europe PMC text mining. Sharing a sentence is not in itself a finding about the gene and the disease. The quoted sentences say what the papers report.
Spastic paraplegia (10 papers, 2013 to 2025). Complete loss of the ability to move the lower limbs accompanied by spasticity of the lower limbs. "We suggest that variants in AP4B1 gene be included in next-generation sequencing panels designed for epilepsy, intellectual disability/developmental delay, spastic paraplegia, and central nervous system malformations." (PMID 32166732, 2020). "Bi-allelic mutations in AP4B1 cause autosomal recessive spastic paraplegia-47(SPG47)." (PMID 32171285, 2020). "Bi-allelic mutations in AP4B1 cause autosomal recessive spastic paraplegia-47 (SPG47, MIM: 614066)." (PMID 32171285, 2020). "It follows that four types of AP‐4‐associated spastic paraplegia do exist, all of them with autosomal recessive inheritance pattern: spastic paraplegia 47 (SPG47)/AP4B1, spastic paraplegia 50 (SPG50)/AP4M1, spastic paraplegia 51 (SPG51)/AP4E1, and spastic paraplegia 52 (SPG52)/AP4S1." (PMID 39723768, 2025). "Four subunits of AP4 (AP4M1, AP4E1, AP4S1, and AP4B1) have been associated with similar autosomal recessive-HSP characterized by progressive spastic paraplegia and severe mental retardation with poor or absent speech development." (PMID 32171285, 2020).
hereditary spastic paraplegia (7 papers, 2020 to 2024). Hereditary spastic paraplegias (HSP) comprise a genetically and clinically heterogeneous group of neurodegenerative disorders characterized by progressive spasticity and hyperreflexia of the lower limbs. "The homozygous truncating variants c.487_488insTAT: p.(Glu163ValfsTer2) and c.664delC (p.(Leu222CysfsTer31) of AP4B1 were first identified to be linked with hereditary spastic paraplegia." (PMID 38906889, 2024). "Our research adds to the genetic variability associated with the SPG11 and AP4B1 variants and emphasizes the genetic heterogeneity of hereditary spastic paraplegia." (PMID 38906889, 2024). "In summary, we show here that a CRISPR-mediated Ap4b1-knockout murine model of human hereditary spastic paraplegia 47 exhibits both behavioural and neuroanatomical deficits that in part mirror those seen in patients." (PMID 36632189, 2023). "Biallelic mutations in the AP4B1 gene, encoding adaptor-related protein complex 4 beta-1 subunit, have been recognized as an important cause of a group of conditions leading to adaptor-related protein complex 4 (AP4)-associated hereditary spastic paraplegia (SPG47)." (PMID 32166732, 2020). "Indeed, mutations in genes encoding all subunits of AP-4 (ε1; AP4E1, β1; AP4B1, μ1; AP4M1 and σ1; AP4S1) have been identified as leading to a complex form of hereditary spastic paraplegia (HSP) termed AP-4 deficiency syndrome (henceforth AP-4 deficiency)." (PMID 31142229, 2020).
Intellectual disability (5 papers, 2013 to 2024). "For instance, most subtypes of CP that involve mental retardation are induced by recessive variations in the genes of 4 protein-binding complexes (AP4M1, AP4E1, AP4S1, and AP4B1)." (PMID 36323241, 2023).
Hydrocephalus (2 papers, 2023 to 2025). Hydrocephalus is an active distension of the ventricular system of the brain resulting from inadequate passage of CSF from its point of production within the cerebral ventricles to its point of absorption into the systemic circulation. "More patients have mild ventricular enlargement caused by non‐hydrocephalus causes, e.g. SPG47/AP4B1, SPG50/AP4M1, SPG51/AP4E1." (PMID 39932116, 2025). "Because hydrocephalus at this stage would most likely cause significant pain in the animals, the absence of any distress or increased mortality in older Ap4b1 (−/−) mice would imply that hydrocephalus is not a common occurrence in these animals." (PMID 36632189, 2023).
AP-4 deficiency syndrome (1 paper, 2023). A genetic disorder associated with variation(s) in the AP4 genes: AP4B1, AP4E1, AP4M1, and AP4S1.
Brain atrophy (1 paper, 2023). Partial or complete wasting (loss) of brain tissue that was once present. "SPG47 patients exhibiting ventriculomegaly are generally clinically diagnosed at a young age, including one case of pre-natal ventriculomegaly, therefore the ventriculomegaly observed in Ap4b1 (−/−) mice might be a consequence of brain atrophy rather than increased CSF volume." (PMID 36632189, 2023).
neuroblastoma (1 paper, 2018). Neuroblastoma (NB) is the most common solid, extracranial childhood tumor. "To determine whether ATG9A is similarly affected by loss of AP-4 in a cell line more relevant to the neuronal phenotypes of AP-4 deficiency, we used CRISPR/Cas9-mediated gene editing to deplete AP4B1 or AP4E1 in mixed populations of SH-SY5Y neuroblastoma cells." (PMID 30262884, 2018).
neurologic disease (2 papers, 2020 to 2024). "Spastic paraplegia 47 (SPG47) is a neurological disorder caused by mutations in the adaptor protein complex 4 β1 subunit (AP4B1) gene leading to AP-4 complex deficiency." (PMID 39358605, 2024).
infection (1 paper, 2024). The state of being infected such as from the introduction of a foreign agent such as serum, vaccine, antigenic substance or organism. "Having confirmed AP4B1 expression from these plasmids, we generated AAV9 viral vectors and transduced AP4B1-KO HeLa cells with two different multiplicities of infection (MOIs), 2 × 105 vg/cell and 4 × 105 vg/cell." (PMID 39358605, 2024).
AP4B1 also shares sentences with these, for which no sentence is quoted: microcephaly (3 papers); cognitive deficits (2); developmental delay (2); epilepsy (2); genetic disease (2); rheumatoid arthritis (2); diabetes type 1 (1); Dystonia (1); febrile seizures (1); gonadal dysgenesis (1); Leigh syndrome (1); leukodystrophy (1); mucolipidosis (1); mucolipidosis II (1); Spasticity (1); systemic lupus erythematosus (1); tetraplegia (1); Ventriculomegaly (1).